BRCA2 (BRCA2 DNA repair associated)
Diseases named in the same sentence as BRCA2 in open-access papers (continued):
Sharing a sentence is not in itself a finding about the gene and the disease.
ovarian carcinoma (continued). "Finally, two pioneer studies using next-generation sequencing techniques reported an 18% prevalence in BRCA1 & BRCA2 (11.3% for BRCA1) mutations in ovarian cancer patients, while the Cancer Genome Atlas (TCGA) Research Network reported 14% (8.5% for BRCA1)." (PMID 23536787, 2013). "Carriers of inherited mutations in BRCA1 and BRCA2 genes face a lifetime risk of ovarian cancer of 35–60% (average age of diagnosis 50 years) and 12–25% (average age of diagnosis 60 years) respectively, and also an elevated risk of fallopian tube and peritoneal carcinomas." (PMID 23536787, 2013). "BRCA1- or BRCA2-mutated ovarian cancer patients are defective of the mechanisms of DNA repairing." (PMID 23577259, 2013). "The BRCA1 and BRCA2 mutations increase the susceptibility to breast or ovarian cancer, and it has been estimated that the probability of developing these forms of cancer is between 30 and 80% in individuals carrying hetero- or homozygous mutations in these genes." (PMID 23675572, 2013). "One important consideration is whether differentials in response to platinum-based chemotherapy between BRCA1- and BRCA2-mutated ovarian cancers observed in recent studies may also be true with respect to the therapeutic response elicited by PARP inhibitors." (PMID 24349831, 2013). "Since ovarian cancers with mutations in BRCA1 or BRCA2 are more sensitive to platinum-containing chemotherapy, we asked whether the total number of somatic mutations in ovarian cancer predicts sensitivity to chemotherapy and clinical outcome." (PMID 24265793, 2013). "The uptake of surgery was related to risk of developing ovarian cancer as demonstrated by a significantly higher uptake in BRCA1 mutation carriers, who have a lifetime ovarian cancer risk of 39–65%, compared with BRCA2 mutation carriers, whose lifetime risks are 10–37%." (PMID 22187038, 2012). "In addition, approximately 10–15% of ovarian carcinomas occur in women with inherited mutations in BRCA1 and BRCA2, who have an estimated 20–50% lifetime risk of ovarian carcinoma." (PMID 22792303, 2012). "The most important high penetrance breast and ovarian cancer susceptibility genes are BRCA1 and BRCA2 but, in addition to breast and ovarian cancer, germline mutations in these genes also increase the risk of prostate cancer and in BRCA2 also of pancreatic cancer." (PMID 23176254, 2012). "It is possible that the improved adjuvant options such as use of aromatase inhibitors in BRCA2 carriers, who have predominantly suffered from ER-positive breast cancers, could have equalised the effect of higher risk of ovarian cancer in BRCA1 carriers." (PMID 22187038, 2012). "Pathogenic mutations in BRCA1 and BRCA2 confer high risks of breast and ovarian cancers." (PMID 22348646, 2012). "The most common mutations in the BRCA1 gene in the families with an increased risk of breast and/or ovarian cancer in Slovenia are c.181T > G, c.1687C > T, c.5266dupC, c.844_850dupTCATTAC and c.181T > A. The most frequent mutations in BRCA2 are c.7806-2A > G, c.5291C > G and c.3975_3978dupTGCT." (PMID 21232165, 2011). "Patients with BRCA1- or BRCA2-linked ovarian cancers were shown to have a longer disease-free interval following chemotherapy and improved survival compared to patients with sporadic ovarian cancer ovarian cancer." (PMID 22312502, 2011).
ovarian carcinoma (continued). "In women with a known BRCA1 or BRCA2 gene mutation the cumulative life-time risk of developing ovarian cancer can be as high as 60% and 27%, respectively, although it may be between 11-39% if the family history is less strong." (PMID 22112691, 2011). "Finally, many tumors also correlate with defects in DDR factors, for example mutations of either BRCA1 and BRCA2 genes predispose to breast and ovarian cancer." (PMID 21926946, 2011). "The BRCA1 and BRCA2 mutation spectrum and mutation detection rates according to different family histories were investigated in 521 subjects from 322 unrelated Slovenian cancer families with breast and/or ovarian cancer." (PMID 21232165, 2011). "The c.156_157insAlu has been described in a Portuguese family as an Alu insertion at codon 52 of BRCA2 and is now considered to be a frequent founder mutation that is detected in nearly one third of breast/ovarian cancer families from northern/central Portugal." (PMID 21939546, 2011). "Deficiency of BRCA1 and BRCA2 is mainly found in breast and ovarian cancers thus far." (PMID 21108794, 2010). "We have followed women at risk for breast and/or ovarian cancer for two decades, and report the prospectively observed age-related annual incidence rates to contract breast or ovarian cancer for women with deleterious BRCA1 or BRCA2 mutations based on 4830 observation years." (PMID 20180971, 2010). "BRCA1 mutations have a higher incidence in ovarian cancer than BRCA2 mutations do." (PMID 23554638, 2010). "BRCA2 germ-line mutations predispose to breast and ovarian cancer." (PMID 18597679, 2008). "Families where FA is due to biallelic BRCA2 mutations will clearly have an increased cancer risk, but these cases are rare (<2% of all FA) and none of the families in this study had a pedigree typical of autosomal dominant breast/ovarian cancer predisposition." (PMID 18786261, 2008). "Germline mutations in BRCA1 and BRCA2 confer a high lifetime risk for breast and/or ovarian cancer, and early studies of familial cancer cases suggested that these risks may be as high as 80%." (PMID 18402691, 2008). "The majority of patients with BRCA1 or BRCA2 associated breast and/or ovarian cancer have a family history, although healthy male carriers may obscure the apparent dominant trait." (PMID 18597679, 2008). "In Spain, a study targeting BRCA1 and BRCA2 mutations in Spanish families with breast/ovarian cancer highlighted a high proportion of variations that appear to be unique to Spaniards, and the existence of recurrent variations associated with the geographical origin of the families." (PMID 18789142, 2008). "Data from several international studies suggest that patients with a loss of heterozygosity of the BRCA1 and BRCA2 genes, which are located on 17q21 and found in hereditary forms of breast cancer, have a 6–61-fold increased lifetime risk of ovarian cancer compared with general population rates." (PMID 17211471, 2007). "The fact that protein-truncating mutations in the BRCA2 gene predispose to breast and ovarian cancers suggests that the hormonal nature of these cancers may be important." (PMID 17700570, 2007). "As individuals heterozygous for BRCA2 mutations have a high lifetime risk of acquiring breast and ovarian cancer, it is likely that alterations in other Fanconi anaemia genes might be associated with an increased risk of breast and ovarian cancer." (PMID 15860134, 2005). "Women with mutations of the genes BRCA1 or BRCA2 are at increased risk of ovarian cancer." (PMID 15545966, 2004). "Since the mapping and the cloning of two genes that confer susceptibility to both breast and ovarian cancer, BRCA1 and BRCA2, it became possible to offer genetic testing to families with a predisposition for breast and/or ovarian cancer." (PMID 15026808, 2004). "Germline mutations in BRCA1 and BRCA2 predispose to breast and ovarian cancer." (PMID 15353005, 2004).
ovarian carcinoma (continued). "Mutations in BRCA1 and BRCA2 both confer greatly elevated risks for ovarian cancer." (PMID 11875732, 2002). "Mutations of BRCA2 in sporadic breast and ovarian carcinomas are exceedingly rare." (PMID 11161375, 2001). "Germline mutations in BRCA1 and BRCA2 genes predispose to hereditary breast and ovarian cancer." (PMID 11237395, 2001). "Additionally, emerging evidence suggests that germline BRCA2 mutations, long associated with breast and ovarian cancers, may also predispose individuals to MM, although findings remain inconsistent across studies." (PMID 41495781, 2026). "Therefore, inhibition of WRN can enhance the cytotoxicity of PARP inhibitors (olaparib) in BRCA2-deficient ovarian cancer cells, suggesting that WRN may be used as an alternative or auxiliary target for PARP inhibitors." (PMID 40649870, 2025). "Furthermore, a detailed medical history and clinical examination must be performed at the beginning of each pregnancy to identify any predisposing genetic factors (such as BRCA1/BRCA2 mutation carrier status or a strong family history of breast or ovarian cancer) or other malignancy risk factors." (PMID 39941758, 2025). "Here, we have approached this question through the lens of BRCA-mutant prostate cancer which, in contrast to breast and ovarian cancer, is largely a BRCA2-mutant disease with a higher percentage of somatic rather than germline cases, as well as frequent 13q copy number loss spanning the BRCA2 gene." (PMID 40460119, 2025). "In the adult cancer literature, a study using data from The Cancer Genome Atlas on patients with ovarian cancer suggests that individuals with BRCA2 variants may have a better outcome due to higher sensitivity to chemotherapy compared with individuals with wild-type genotypes." (PMID 38546643, 2024). "Additionally, recent studies suggest that BRCA1/BRCA2, well-known tumor suppressor genes frequently mutated in hereditary breast and ovarian cancers, may play a role in autophagy regulation." (PMID 39199310, 2024). "This suggests that a tailored clinical approach may be necessary for BRCA 2 mutation-associated prostate cancer, similar to the personalized therapeutic approach for BRCA2-associated breast and ovarian cancers, both of which are particularly sensitive to platinum-based." (PMID 39364320, 2024). "Our previous study has demonstrated that increased expression of aldehyde dehydrogenase 1A1 (ALDH1A1) contributes to PARPi resistance in BRCA2-mutated ovarian cancer cells by enhancing microhomology-mediated end joining (MMEJ) but the mechanism remains unknown." (PMID 37429899, 2023). "Also, while the distinction in sensitivity between BRCA1 and BRCA2-associated ovarian cancers remains unclear in the clinical setting, emerging in vitro data does indicate that all BRCA mutations are not equal in their functionality." (PMID 37415740, 2023). "However, if BRCA2 was involved one would expect that ovarian cancer risk was also increased." (PMID 34117277, 2021). "In addition, the frequency of germline BRCA1/2 gene mutation carriers and the ratio of germline BRCA1 to BRCA2 mutations in ovarian cancer patients may vary depending on the population." (PMID 34356066, 2021). "However, BRCA2 mutations were readily reported in all of those populations, suggesting that BRCA2 mutations might be less prevalent in the Vietnamese patients with breast or ovarian cancers." (PMID 35070997, 2021). "Importantly, STAT3 blockade led to Olaparib-resistant cell growth inhibition, and lower Napabucasin concentrations re-sensitized resistant BRCA-wildtype and BRCA2-mutated ovarian cancer cells to Olaparib in vitro, further supporting the notion that STAT3 activity promotes PARPi resistance." (PMID 34956861, 2021). "Moreover, a loss of function in BRCA1 and BRCA2 most commonly occurs in breast and ovarian cancers." (PMID 34830749, 2021).
ovarian carcinoma (continued). "In addition to 13.7% of deleterious germline BRCA1/BRCA2 carriers, we identified 7.4% additional patients with pathogenic germline variants in other genes predisposing for ovarian cancer, namely RAD51C, RAD51D, and MSH6, representing 35% of all pathogenic germline variants." (PMID 33008098, 2020). "Therefore, we speculated that the mutations between BRCA1 and BRCA2 synergistically lead to the occurrence of ovarian cancer in this family." (PMID 32356124, 2020). "Interestingly, approximately a quarter to half of ovarian cancers with germline BRCA1/BRCA2 mutations exhibit the reversion of the inherited mutation and chemoresistance after chemotherapy, suggesting that in vivo retrieval of BRCA function is a potent oncogenic event to resist unwanted DNA damage." (PMID 32269964, 2020). "Comprehensive BRCA1 and BRCA2 genetic testing could, however, identify more women with pathogenic variants, thus leading to improved cancer prevention for more women at high risk of breast and ovarian cancer." (PMID 32772980, 2020). "Importantly, BRCA1 and BRCA2 are often mutated or inactivated in spontaneous ovarian cancer." (PMID 30042330, 2018). "Our literature search shows that variation in the prevalence of high-penetrance alleles in genes such as BRCA1 and BRCA2 may contribute to the reported differences in breast and ovarian cancer incidence across India, in Indians in other countries, and between India and the west." (PMID 35693198, 2018). "Examination of the sensitivity, specificity, accuracy and MCC for a set of BRCA1 and BRCA2 mutations alone sheds little light on the amounts of patients that would be affected by misleading findings in a clinical setting, e.g., genetic testing in families at risk for breast and ovarian cancer." (PMID 29580235, 2018). "However, secondary mutation of BRCA2 can elicit cisplatin resistance in ovarian carcinomas." (PMID 30001383, 2018). "We also examine numbers of carrier tests performed for family members of each BRCA1 and BRCA2 mutation positive identified ovarian cancer patient, as prevention efforts rely on uptake of carrier testing in family members who have yet to be diagnosed with ovarian cancer." (PMID 29506471, 2018). "Because women with BRCA1 and BRCA2 mutations are already at high risk of developing breast and ovarian cancers, the combined effects of risk-modifying variants could lead to much larger differences in the absolute risk of developing the disease as compared with the general population." (PMID 28376175, 2017). "For this reason, it is important that effective mechanisms for disseminating new research findings are adopted because if mutations in BRCA1 or BRCA2 can be identified and at-risk relatives are able to adopt preventive measures, the incidence of ovarian cancer may be reduced." (PMID 26574041, 2017). "Breast cancer 1 antigen (BRCA 1) and breast cancer 2 antigen (BRCA2) genes play a significant role in deoxyribonucleic acid (DNA) repair by means of interstrand crosslink repair, and deleterious germline mutations of these are responsible for most hereditary breast and ovarian cancers." (PMID 28959512, 2017). "To test whether the expansion of SOX2-expressing cells occurred prior to HGSOC development, we analyzed the fallopian tubes of 48 women at high risk of developing ovarian cancer because they were BRCA1 or BRCA2 gene mutation carriers and therefore underwent prophylactic salpingo-oophorectomy." (PMID 27492892, 2016).
ovarian carcinoma (continued). "Since the majority of both BRCA1 and BRCA2 ovarian cancer associated cancer tumors are high-grade serous to increase the power of the association analyses, a meta-analysis combining HRs for the association of variants with ovarian cancer risk in BRCA1 and BRCA2 was conducted." (PMID 27463617, 2016). "Thus the existing figure for the BRCA1 and BRCA2 mutation carrier frequency in French Canadian women with ovarian cancer may be an underestimate." (PMID 25884701, 2015). "In the present study, we show that the use of the Ion Torrent PGM sequencer to sequence the coding exons of BRCA1 and BRCA2 genes substantially improves the detection rates of a wide spectrum of mutations in Polish patients with familial and/or only early onset of breast and/or ovarian cancers." (PMID 25948282, 2015). "In conclusion, this systematical meta-analysis regarding the association between BRCA2 N372H polymorphism and cancer risk revealed that this polymorphism was significantly associated with an increased risk of overall cancer, and the association was also observed for ovarian cancer." (PMID 25348552, 2014). "Poly(ADP-ribose) polymerase (PARP) inhibitors, which are especially effective in cancer associated with BRCA1 or BRCA2 mutation, have shown considerable promise in triple-negative breast cancer and may be valuable in treating high-grade serous Type II ovarian cancer." (PMID 23536770, 2013). "Thus, a large-scale MLPA exploration of 1506 German families for pathogenic genomic rearrangements in the BRCA1 gene and of 450 families for gross rearrangements in BRCA2 showed that in high-risk groups for hereditary breast and ovarian cancer, the prevalence of rearrangements was 2.1%." (PMID 23344037, 2013). "Likewise, BRCA1 and BRCA2 participate in error-free repair of double-strand DNA breaks by homologous recombination (HR) and inherited mutations in these genes predispose to breast and ovarian cancers." (PMID 24265793, 2013). "In addition to the hereditary breast and ovarian cancer syndrome caused by germline mutations in BRCA1 and BRCA2, ovarian cancer is also present in the Lynch syndrome that is caused by germline mutations in DNA mismatch repair genes and characterized by susceptibility to colorectal cancer." (PMID 23176254, 2012). "Nonetheless, BRCA1 and BRCA2 proteins appear to share a number of functional similarities that may suggest why mutations in these genes lead to specific hereditary predisposition to breast and ovarian cancer." (PMID 20579331, 2010). "Consequently, large genomic rearrangements in BRCA1 and BRCA2 might still be at least partly responsible for the hereditary predisposition to breast and ovarian cancer in Finland." (PMID 18501021, 2008). "The identification of BRCA2 as a member (FANCD1) of the Fanconi anaemia group of genes has raised the possibility that variation in other Fanconi anaemia genes may predispose to breast or ovarian cancer." (PMID 15860134, 2005). "However, higher expression from Xp11 may be related to the earlier age of presentation of epithelial ovarian cancers in BRCA1 mutation carriers compared to tumors in BRCA2 mutation carriers and patients with sporadic ovarian cancer." (PMID 15383145, 2004). "The article presents the current state of knowledge on genetic modifiers of ovarian cancer risk in women carrying pathogenic variants (PVs) in the BRCA1 and BRCA2 genes, which are major contributors to hereditary susceptibility to this malignancy." (PMID 41681824, 2026). "Risk-reducing salpingo-oophorectomy (RRSO) is the most effective intervention for reducing ovarian cancer risk in women with hereditary breast and ovarian cancer syndrome (HBOC) associated with pathogenic BRCA1 and BRCA2 variants." (PMID 41717173, 2026). "Ovarian cancer with BRCA1/BRCA2 inactivation similarly shows heightened sensitivity to DNA-damaging therapy." (PMID 40841483, 2026).